IL23R (interleukin 23 receptor)
Diseases named in the same sentence as IL23R in open-access papers (continued):
Sharing a sentence is not in itself a finding about the gene and the disease.
ankylosing spondylitis (45 papers, 2009 to 2025). An autoimmune chronic inflammatory disorder characterized by inflammation in the vertebral joints of the spine and sacroiliac joints. "The IL-23R locus has been linked to several autoimmune diseases such as inflammatory bowel disease, Behçet’s disease, Psoriasis, and Ankylosing Spondylitis." (PMID 38892265, 2024). "Through investigating genetic variations, it has been demonstrated that single nucleotide polymorphisms (SNPs) in the IL-23 receptor (IL23R) gene have a critical role in the pathophysiology of ankylosing spondylitis (AS)." (PMID 38605394, 2024). "The association between the IL-23R and IL-17A polymorphisms and ankylosing spondylitis (AS) in the Southwest Chinese Population is still unclear." (PMID 29050281, 2017). "The interleukin-23 receptor (IL-23R) has been shown to be associated with ankylosing spondylitis (AS) in many different populations." (PMID 23840727, 2013). "Genome-wide association studies performed in the axial and more severe form (i.e., ankylosing spondylitis [AS]) have revealed significant genetic associations with several polymorphisms involved in the T helper 17 cell (Th17) pathway: IL-23 receptor (IL-23R), IL-12B, IL-1R2, IL-6R, and RUNX3." (PMID 33488572, 2020). "First, genome-wide association studies (GWAS) studies have clearly established that SNPs in the IL-23R are a susceptibility factor for ankylosing spondylitis and several other genetic risk factors associated with ankylosing spondylitis also point toward the IL-23/IL-17 axis." (PMID 33679714, 2020). "The IL23R region on chromosome 1 exhibits complex associations with ankylosing spondylitis (AS)." (PMID 28381868, 2017). "Furthermore, polymorphisms of IL23R are a risk factor for ankylosing spondylitis (AS) and psoriatic arthritis (PsA), which indicates that IL-23 is also involved in the pathogenesis of spondyloarthritis (SpA)." (PMID 28850053, 2017). "However, IL-17A belongs to an immune axis with IL-23 and the association of a variant (rs11209032) ∼15 kb downstream of the gene encoding the IL-23 receptor (IL23R) with ankylosing spondylitis thus provided a rationale for repositioning secukinumab to treat this additional inflammatory disease." (PMID 29270124, 2017). "Among them, AIF1 and IL23R are associated with decreased risk of ankylosing spondylitis; MICA, MAPK14, and ATF6B are linked to increased risk of ankylosing spondylitis." (PMID 38835753, 2024). "The proportion of IL-23R-expressing T cells in the periphery was 2-fold higher in ankylosing spondylitis (AS) patients than in healthy controls, specifically driven by a 3-fold increase in IL-23R-positive γ/δ T cells in AS patients." (PMID 26678098, 2015). "However, association with ankylosing spondylitis in East Asians was observed at IL23R for a low-frequency non-synonymous SNP, rs76418789 (OR = 1.5, P = 8.2 × 10−4)." (PMID 26375822, 2015).
colitis (42 papers, 2010 to 2025). Inflammation of the colon. "Studies have indicated that Batf1-dependent IL-23R+IL-6+CD4+ Th17 cells are crucial for regulating IL-23-driven colitis-associated tumor formation and the progression of sporadic colon tumors." (PMID 39796684, 2024). "In innate (lymphocyte independent) colitis model, IL-23R-related pathology was associated with IL-22 signaling, as neutralization of IL-22 exhibited protectivity." (PMID 39354587, 2024). "Il23r-deficient mice lacks Il22 expression, and IL-23R-mediated IL-22 production is considerably important for improving colitis." (PMID 34759916, 2021). "To assess the functional role of IL-23R signalling, we induced colitis in wild type (WT) or IL-23R-deficient (Il23r−/−) mice by infection with Hh+anti-IL-10R." (PMID 27193261, 2016). "Similarly, IL-23R-dependent IL-22 production caused intestinal inflammation in an innate colitis model that was induced in immune-deficient mice by administration of anti-CD40 mAbs." (PMID 29075900, 2018). "A more complex scenario emerged however from studies in chronic CD45RB (high) CD4+ T cell transfer and anti-CD40 antibody-induced acute innate colitis models in Rag1-deficient mice showing that IL-23R signaling in ILCs3 is protective in the former and pathogenic in the latter." (PMID 25061260, 2014). "Furthermore, it was shown that IL-23R signaling promotes innate colitis via IL-22 as neutralization of IL-22 protects mice from colitis and the adding back of IL-22 to IL-23R-deficient animals restores the disease." (PMID 25061260, 2014). "Considering that anti-TNF-α immunotherapy, while employed in IBD, is not universally effective and that newer therapies targeting IL-23R or IL-17, which play a detrimental role in colitis, are costly, iTcES represents a promising biotherapeutic alternative." (PMID 40576745, 2025). "In an experimental colitis model, IL-23R signaling was observed to decrease the frequency of Tregs in the gut and impair their suppressive functions, potentially due to a reduction in Foxp3 expression." (PMID 39796684, 2024). "In DSS-induced colitis IL-23R signaling by mature lymphocytes reduced pathology but in the absence of lymphocytes IL-23 signaling promotes pathology, indicating dichotomy in the function of the IL-23 pathway in adaptive versus innate immune compartments." (PMID 39354587, 2024). "The expression of IL-23R by activated granulocytes has been demonstrated in murine models of colitis or aspergillosis." (PMID 39796684, 2024). "In murine models of colitis, inhibiting the function of IL-12 or IL-23r was confirmed to suppress the inflammatory response dramatically." (PMID 36084127, 2022). "IL-23R-mediated signaling stimulates epithelial cells to produce RegIIIβ, which then recruits IL-22-producing neutrophils capable of improving colitis." (PMID 29075900, 2018). "Mice that received Il23r−/− naive T cells were completely protected form colitis compared with WT naive T-cell recipients with maintenance of body weight, colonic length and reduced colonic inflammation." (PMID 29725003, 2018). "This is in line with previous work showing that both anti-CD90 (Thy-1) depletion in Rag1-deficient mice or use of Rag1.Rorc-double deficient mice, which principally lack IL-23R+ innate lymphoid cells, are similarly resistant to anti-CD40-induced colitis." (PMID 24586521, 2014). "Our results also raise the possibility that the requirement for RORγt expression in T cells for development of T cell transfer colitis reflects the known activities of RORγt in promoting Il23r expression on T cells." (PMID 20732640, 2010). "Additionally, activated granulocytes have been shown to express IL-23R in inflammatory murine models of colitis and aspergillosis." (PMID 40297579, 2025).
colitis (continued). "The deletion of the IL23 receptor (IL23R) in IECs disrupts microbiota composition with an expansion of flagellated bacteria and elevated death rate caused by colitis, which suggests that IL23 has a protective effect in inflammation-induced colitis." (PMID 39767678, 2024). "Whereas, rCsCP ameliorated the acute colitis might through activating innate immunity, downregulating the expression of pro-inflammatory factors (IL-12, IL-23r and IL-7), and promoting the production of anti-inflammatory factors (IL-10, IL-4 and IL-13)." (PMID 36084127, 2022). "We conclude that REX-secreting L. lactis strains were engineered that might serve as IL-23/IL-23R blockers in an experimentally induced mouse model of colitis." (PMID 31137908, 2019). "Here, we show that T-bet expression by T cells is not required for the induction of colitis or the differentiation of pathogenic Th17 cells but modifies qualitative features of the IL-23-driven colitogenic response by negatively regulating IL-23R expression." (PMID 27193261, 2016). "In addition, it has been suggested that IL23R+ ILCs can induce colitis via an IL-22-dependent pathway." (PMID 27578924, 2016). "Indeed amelioration of colitis with GM-CSF blockade was similar to that observed with anti-IL-23R mAb treatment." (PMID 26780670, 2016). "To assess the role of IL-23R expression on T cells in the development of colitis, we transferred CD4+CD45RBhi cells isolated from wild-type (WT) or Il23r−/− mice into B and T cell-deficient Rag1−/− mice, with the latter allowing us to restrict IL-23 responsiveness to the innate immune compartment." (PMID 20732640, 2010). "Moreover, a murine model with CD4+ T cells lacking the IL23R has revealed that IL23R signaling induces colitis, associated with the induction of IFNγ and IL17A co-expressing cells." (PMID 33859636, 2021). "Although the Th17-cell subset is most prominently associated with IL-23R function, our recent work suggests that the immunopathology driven by Red 40 and IL-23 does not depend on classical Th17 responses, as blocking IL-17A and IL-17F fails to prevent colitis development in R23FR mice." (PMID 35468944, 2022). "Thus, in the presence of IL-23R-responsive WT T cells there is a reduction in the ability of Il23r−/− T cells to produce IL-10, which may explain the development of colitis in mice given a mixture of WT and Il23r−/− T cells, despite increases in the percentage of Foxp3+ Treg cells." (PMID 20732640, 2010). "Upon transfer into Rag1−/− mice, in vitro-induced Th1-like cells accumulate in the colon and mediate spontaneous colitis; however, the transfer of Il23r−/− Th1-like cells did not result in colitis." (PMID 39379604, 2024). "Despite the findings of exacerbated TNBS-colitis in mice lacking the p19 subunit of IL-23, novel therapies targeting IL-23 and the IL-23R have been developed and deemed successful when tested in clinical trials of patients with IBD." (PMID 36012618, 2022). "In favor of this hypothesis is the higher IL-23R expression in vivo in Tec−/− Th17, IFN-γ+Th17, and Th1/exTh17 cells from small intestine of animals with colitis." (PMID 35003062, 2021). "Taken together, our data show enhanced IL-23R-positive cells with higher receptor levels among eYFP+ cells in the intestine in the absence of Tec during onset of colitis." (PMID 35003062, 2021). "In fact, T cells selectively lacking IL-23R through genetic inactivation similarly fail to mediate colitis in this model system." (PMID 33584655, 2020). "Dissimilarly, rCsCP ameliorated colitis mainly through stimulating innate immunity, such as Toll like receptor (TLR) signaling pathway, down-regulating the expression of inflammatory cytokines (e.g., IL-12b, IL-23r and IL-7), thereby restraining the differentiation of Th1/Th17 cells." (PMID 36084127, 2022).
colitis (continued). "Although colitis in this model was accredited to the production of the Th1 cytokine IFN-γ, enhanced emergence of IL-17A+IFN-γ population of T cells and suppression of populations of Foxp3+ and IL-10-producing regulatory T cells was attributed to IL-23R signalling in T cells." (PMID 36012618, 2022). "Indeed, IL-23 persistence induces Th17 to acquire a Th1-like phenotype, and lack of IL-23R on T cells prevents experimental colitis." (PMID 34630512, 2021). "As IL-23R signals are central to upregulation of IL-1R by Th17 cells and IL-1R confers pro-survival signals for accumulation of T cells in the colon, the IL-23/IL-1 axis plays most likely an important role for the differences seen in the DC-LMP1/CD40-model for colitis." (PMID 30653608, 2019). "Therefore, although GM-CSF could be from other sources, on the basis that they are IL-23R-expressing cells and neighbors of IL-23-producing cells, ILC3s appeared to be an irreplaceable effector population in α-DR3-exacerbated innate colitis." (PMID 31358760, 2019). "However, as the IL-23R is upregulated in Th17 cells in the T-cell-driven colitis model in the absence of Tec, it is tempting to speculate that Tec kinase regulates Th17 plasticity in an Th17-intrinsic mode by acting in the IL-6R signaling pathway." (PMID 35003062, 2021).
ulcerative colitis (35 papers, 2007 to 2026). An inflammatory bowel disease involving the mucosal surface of the large intestine and rectum. "Since a genome-wide association study revealed that Interleukin-23 receptor (IL-23R) gene is a candidate gene for Ulcerative Colitis (UC), many studies have investigated the association between the IL-23R polymorphisms and UC." (PMID 27902482, 2017). "A novel association with ulcerative colitis susceptibility occurred in haplotypes of IL23R (Block1 H3 P = 0.02; Block2 H2 P = 0.019; Block3 H4 P = 0.029) and IL17A (H4 P = 0.034)." (PMID 22984500, 2012). "Our study demonstrated that rs7530511, and rs11805303 of IL23R were significantly associated with ulcerative colitis susceptibility in the Chinese population." (PMID 22984500, 2012). "Compared to the healthy controls, the variant alleles IL23R rs7530511, and rs11805303 showed a statistically significant difference for ulcerative colitis susceptibility (0.7% vs 3.3%, P = 0.002; 60.4% vs 53.2%, P = 0.0017, respectively)." (PMID 22984500, 2012). "A total of 270 ulcerative colitis and 268 healthy controls were recruited for the analyses of 23 SNPs in the IL23R and IL17A regions." (PMID 22984500, 2012). "This study examined the association of IL23R and IL17A gene SNPs with ulcerative colitis susceptibility in a population in China." (PMID 22984500, 2012). "The most noticeable finding was the linkage of IL23R and IL17A gene region to ulcerative colitis risk due to the gene-gene interaction." (PMID 22984500, 2012). "Variants in IL‐23R and NOD2 strongly influence IBD susceptibility, and recent work has highlighted how targeting the IL‐23/Th17 axis can translate these findings into effective biologic therapies in CD and ulcerative colitis." (PMID 41487707, 2026). "Thus, polymorphisms in genes, such as NOD2/CAR15, ATG16L1, IL23R, and IL10R have been involved in susceptibility to pIBD or to very-early-onset ulcerative colitis." (PMID 32397546, 2020). "However, IL23R was not involved in susceptibility to ulcerative colitis in the Finnish population." (PMID 19175939, 2009).
systemic lupus erythematosus (24 papers, 2010 to 2025). An autoimmune multi-organ disease typically associated with vasculopathy and autoantibody production. "IL-23 and IL-23R are essential for expansion of pathogenic IL-17-producing T lymphocytes and have been shown to be important in the pathogenesis of lupus in animal models." (PMID 21110900, 2010). "This is consistent with a previous study using a lupus animal model, which showed that IL-23R-deficiency prevented the development of lupus nephritis in lpr/lpr mice." (PMID 21110900, 2010). "IL-23 and its receptor IL-23R are necessary for the proliferation of pathogenic IL-17-producing T cells shown to be critical for lupus pathogenesis, and IL-23R-deficit prevents the development of lupus nephritis in lupus-prone mice." (PMID 34484186, 2021). "We observed that in vivo expression of IL-23 alone was sufficient to drive the expansion of DN T cells without affecting the integrity of MZM barrier, which is consistent with our previous reports that Il23r-deficient lupus-prone B6.lpr mice have decreased numbers of DN T cells." (PMID 32503973, 2020). "Good examples of known shared risk loci in IMDs are PTPN22, IL23R and TNFAIP3, which have allowed the repositioning of anti-TNF and anti-IL-12/IL-23 therapies to be used in rheumatoid arthritis (RA) and systemic lupus erythematosus (SLE), among others." (PMID 33317201, 2020). "In RA, IL23R is upregulated on mRNA level but not on protein level by the EP2-specific agonist butaprost, while IL23R mRNA is decreased in systemic lupus erythematosus (SLE) by activation of EP2 or EP4." (PMID 31253169, 2019). "Interleukin 23 receptor expressing IL-17 producing T cells have been shown to be important in the development of murine lupus." (PMID 23841097, 2013). "Similarly, B6.lpr−/− lupus-prone mice devoid of IL-23R abrogated the development of LN, coupled with a reduction of the number of DNTC, IL-17A-producing cells in lymph nodes and anti-dsDNA antibody production." (PMID 35326431, 2022). "In addition, MRL/lpr lupus-prone mice knocked out for IL-23 receptors (IL-23R) revealed less severe LN, which was mechanistically explained by the restoration of IL-2 and a decrease in IL-17 production by T cells, together with reduced TFH and APCs, and reduced anti-dsDNA levels." (PMID 35326431, 2022). "One another possible explanation is that IL-23R gene polymorphisms were associated with organ-specific autoimmune diseases, such as ankylosing spondylitis, psoriasis, or inflammatory bowel disease, but not with systemic autoimmune diseases, such as RA and systemic lupus erythematosus (SLE)." (PMID 35216226, 2022). "Some reports suggest that estrogen receptor α (ERα) signaling increases IL-17A production in Th17 cells by upregulating IL-23R expression in a Let-7f-dependent manner, and this might be a reason for the increasing prevalence of systemic lupus erythematosus (SLE) and multiple sclerosis in women." (PMID 33816637, 2021). "In IL-23R KO/lpr mice, which do not develop lupus, the total number of DN T cells as well as the total number of IL-17A producing DN T cells and CD4+ T cells was decreased." (PMID 30858513, 2019). "Previous studies have shown that deletion of IL-23R in B6/lpr and MRL/lpr mice reduced DN T, IFNγ- and IL-17- producing cells, suppressed anti-dsDNA autoantibodies and total IgG production, reduced immune complex deposition, and ameliorated lupus nephritis in the lpr lupus mice." (PMID 35784356, 2022).
rheumatoid arthritis (21 papers, 2008 to 2026). A chronic, systemic autoimmune disorder characterized by inflammation in the synovial membranes and articular surfaces. "Several SNPs in the IL-23R gene have recently been shown to be associated with autoimmune and inflammatory conditions, including Crohn's disease, rheumatoid arthritis (RA), and psoriasis." (PMID 22242199, 2012). "Additionally, B. longum RAPO significantly inhibited Th17 cells and Th17-related genes—IL-17A, IRF4, RORC, IL-21, and IL-23R—in the PBMCs of rheumatoid arthritis patients." (PMID 34867956, 2021). "Both miR-126 and IL-23R affect rheumatoid arthritis (RA) procession." (PMID 30167920, 2018).